LINC01816 (long independently transcribed non-coding RNA 1816)
Synonyms: LOC100133985
Gene: Long non-coding RNA gene on chromosome 2 (70,093,885 to 70,142,950, reverse strand). Ensembl gene ENSG00000231327.
Diseases named in the same sentence as LINC01816 in open-access papers:
LINC01816 is named in the same sentence as 2 diseases in open-access papers, as found by Europe PMC text mining. Sharing a sentence is not in itself a finding about the gene and the disease. The quoted sentences say what the papers report.
gastric cancer (1 paper, 2019). A primary or metastatic malignant neoplasm involving the stomach. "LncRNA LINC01816 is down-regulated and might be protective factor in gastric cancer." (PMID 30782113, 2019).
thyroid carcinoma (1 paper, 2021). "LINC01816 was found to promote the migration of thyroid carcinoma cells." (PMID 34603485, 2021).